MTOR (mechanistic target of rapamycin kinase)
Diseases named in the same sentence as MTOR in open-access papers (continued):
Sharing a sentence is not in itself a finding about the gene and the disease.
tumor (continued). "Emerging studies reveal that mTOR-driven TNBC progression involves sophisticated crosstalk with autophagy machinery, forming reciprocal regulatory circuits that maintain a proliferation-permissive tumor microenvironment." (PMID 41009794, 2025). "In this scenario, it has been demonstrated that genistein, by acting on specific signaling pathways (i.e., Sonic Hedgehog (SHH), Wnt/β-catenin, Notch, NF-κB JAK-STAT, PI3K/Akt/mTOR signaling), affects CSC proliferation, thereby inhibiting tumor invasiveness and metastasis." (PMID 39940882, 2025). "The infiltration of the tumor stroma by immune cells is a process that is not yet fully understood, with some determinants of the process such as mechanistic target of rapamycin(mTOR) only having been recently described." (PMID 40563621, 2025). "In HCC, it exerts its anti-tumor effects via a dual mechanism: classically, by impairing 28S rRNA methylation, and non-classically, by inhibiting the phosphorylation of the mTOR pathway effector 4EBP1." (PMID 41301542, 2025). "Thus, we suggested that RNASEH2C enhanced tumor progression by increasing TRAF3IP1 expression and inhibiting the mTOR pathway." (PMID 41361104, 2025). "The downregulation of p-PI3K and p-AKT confirms suppression of survival signaling, while the inhibition of key oncogenic regulators AKT1, MTOR, HIF1A, SRC, and ESR1 suggests broader effects on tumor metabolism, hypoxia adaptation, and growth factor receptor pathways." (PMID 40746726, 2025). "It was further established that mTOR inhibitors augmented IRT response of tumor cells both in vitro and in vivo, irrespective of the timing as well as the schedule of mTOR blockade." (PMID 41498028, 2025). "Circ-FBXW7 acts as a tumor-suppressive RNA by regulating NEK2, mTOR, and PTEN pathways." (PMID 41373479, 2025). "By preventing the PI3K/Akt/mTOR pathway from being activated, the exosomes containing CTX and TRAIL showed synergistic antitumor effects and triggered apoptosis, which resulted in a considerable tumor suppression and tumor volume decrease." (PMID 40530018, 2025). "Furthermore, numerous immune-tumor interaction pathways (e.g., MAPK, PI3K/Akt/mTOR, ErbB/EGFR) varied between MBM and ECM." (PMID 40954493, 2025). "Thus, PRR15 silencing demonstrably compromised Akt-mTOR signaling, resulting in consequent suppression of proliferation, induction of apoptosis, and ultimately, impeded NSCLC xenograft tumor growth." (PMID 39929816, 2025). "In non-immune TME, tumor cell growth is mainly regulated by the PI3K/AKT/mTOR signaling pathway, RAS/RAF/MAPK signaling pathway, and WNT/β-catenin signaling pathway." (PMID 40013141, 2025). "However, there is no such study available on direct effect of rutin on VEGFR-2 but it has been reported that rutin exerts its tumor inhibitory effect through the regulation of signaling pathways like Jun N-terminal kinase (JNK), MAPK, p38, PI3K/Akt/mTOR." (PMID 39831267, 2025). "Similarly, in vivo studies demonstrated that APOC1 knockdown significantly reduced tumor growth, angiogenesis-related proteins, and phosphorylated PI3K/AKT/mTOR pathway proteins in nude mice." (PMID 39873475, 2025). "Activation of the PI3K/AKT/mTOR signaling cascade in tumor cells leads to a feedback increase in sodium–glucose co-transporter (SGLT) 1 and activates glycolysis, thereby promoting Tamoxifen resistance and accelerating tumor growth both in vitro and in vivo." (PMID 39941714, 2025). "This distinction underscores the complexity of mTOR pathway regulation in UCS and indicates that TSC2 and PIK3CA may exert their effects on tumor biology via divergent mechanisms." (PMID 41181577, 2025).
tumor (continued). "Moreover, it reduced the levels of phosphorylated AKT and p70S6K in a dose- and time-dependent manner, indicating that YYN-37′s anti-tumor efficacy is mediated through the suppression of PI3K and mTOR kinase activities." (PMID 41471338, 2025). "Translational profiling of normal, non-metastatic tumor vs. metastatic tumor cells implicates translational reprogramming by MTOR as a driver of prostate cancer invasion and metastasis." (PMID 41239272, 2025). "AZGP1 acts as a tumor suppressor mainly by inhibiting proliferation, migration, and invasion by negatively interfering with epithelial mesenchymal transition (EMT) induced by TGFβ signaling as well as PTEN/AKT/mTOR pathways." (PMID 39851496, 2025). "Similarly, the steroidal saponin C21 extracted from Marsdenia induces protective autophagy in GC cells by inhibiting the PI3K/AKT/mTOR signaling pathway, while activating the PTEN/AKT/mTOR signaling pathway to induce apoptosis of tumor cells." (PMID 40066330, 2025). "Additionally, UA's ability to target key signaling pathways, including AKT, mTOR, and NRF2, enhances the anti-tumor efficacy of the combination therapies, while also reducing drug resistance." (PMID 40490812, 2025). "Beyond metabolism, ERRα enhances tumor cell survival by upregulating anti-apoptotic and proliferative genes such as BCL2, Cyclin D1, and c-Myc, and by activating key oncogenic signaling pathways like PI3K/Akt/mTOR and MAPK/ERK." (PMID 40926269, 2025). "KO tumour‐prone cells also displayed enhanced activity in glycolysis, the TCA cycle, and macromolecule synthesis pathways (lipids, amino acids, and glycans), alongside mTOR pathway activation." (PMID 40887856, 2025). "Preclinical findings show that these compounds are highly selective towards mTOR as opposed to other kinases such as P13K, significantly inhibiting S6K and 4E-BP phosphorylation and inducing anti-tumour activity." (PMID 40805230, 2025). "Mammalian target of rapamycin (mTOR) inhibitors, typified by sirolimus, demonstrate efficacy in tumor progression control but are not devoid of adverse reactions." (PMID 40852360, 2025). "Rapamycin, an mTOR inhibitor, context-dependently induces senescence, diminishes NF-κB activity, suppresses pro-inflammatory SASP translationally, and attenuates senescence-mediated tumor promotion." (PMID 40703657, 2025). "There is ongoing research into mTOR inhibitors as a potential therapy for this extremely rare tumor, as no effective therapy has been established." (PMID 40558273, 2025). "Targeting key metabolic pathways, such as IDO, mTOR, and AMPK, could provide new therapeutic avenues to overcome immune suppression and enhance anti‐tumor immunity." (PMID 40874420, 2025). "Immunohistochemical analysis of 3D heterotypic tumor spheroids confirmed that both individual and combined treatment with TAS-115 and DOXO reduced the expression of c-MET, p–c-MET, and p-mTOR, a key node in the PI3K/Akt/mTOR pathway." (PMID 41289612, 2025). "While metformin was detectable at measurable levels within the prostate, it did not significantly change tumor cell proliferation, apoptosis, or mTOR pathway markers compared to placebo." (PMID 41050082, 2025). "Other recurrent integration sites include the FAT atypical cadherin 2 gene, which activates genes regulating epithelial-mesenchymal transition, the mTOR pathway, and intergenic regions, suggesting that HBV contributes to tumor progression through multiple molecular pathways specific to iCCA." (PMID 41008893, 2025). "Additionally, PTTG1 influences angiogenesis by regulating VEGF expression through HIF-1α and the PI3K/AKT/mTOR pathway, thereby enhancing CSC survival and tumor progression." (PMID 40072059, 2025). "Vitronectin/mTOR; IL-8/PI3K/Akt/NF-κB promotes tumor metastasis." (PMID 41294885, 2025).
tumor (continued). "Similarly, the detection of corresponding proteins in the tumor tissues of nude mice with TNBC revealed that PVT effectively downregulated the protein expression levels of PTP1B, PI3K, AKT and mTOR in tumor tissues." (PMID 40076586, 2025). "Studies considering various tumor types have reinforced the importance of cell cycle suppression by inducing cell entrapment in G0/G1 through the inhibition of EGFR/MAPK and PI3K/mTOR." (PMID 40650170, 2025). "By orchestrating signaling cascades, such as AMPK/mTOR, Wnt/β-catenin, and AKT/AMPK, and reprogramming metabolic pathways including glycolysis, lipid metabolism, and the tricarboxylic acid cycle, HKDC1 enhances tumor aggressiveness and chemoresistance." (PMID 41049000, 2025). "While mTOR and TGF‐β signaling inhibitors and drugs targeting metabolic pathways have shown promise in BC therapy, their efficacy often encounters challenges such as tumor heterogeneity." (PMID 40926349, 2025). "We subsequently elucidated the tumor-suppressive functions of MFAP4 in TNBC and, for the first time, uncovered a mechanistic axis whereby extracellular MFAP4 negatively regulates the intracellular PI3K/AKT/mTOR signaling pathway." (PMID 41451212, 2025). "Gain in mTOR and PI3K activity, gain-of-function of AKT, and decreased or lost function of PTEN are common promoters of treatment resistance and disease progression in neoplasia." (PMID 40183103, 2025). "Lastly, as mTOR was overexpressed in DLBCL compared with control samples, we investigated its expression in CD86+ cells in DLBCL samples (intra-T vs peri-T) and in DLBCL vs non-tumor control (lymph nodes) samples." (PMID 41415285, 2025). "Due to the significant role of Akt1 in tumor progression and drug resistance, coupled with the documented efficacy of flavonoids in targeting the PI3K/Akt/mTOR pathway, the present study aimed to evaluate the binding affinity of a set of 61 herbal flavonoids to the Akt1 ATP‐binding domain." (PMID 40798865, 2025). "We next assessed whether activation of mTOR/S6K signaling pathway in BBB glia is sufficient to rescue the decrease in glial number and tumor size induced by NR." (PMID 41252380, 2025). "Moreover, the activation of major oncogenic pathways, such as PI3K/Akt/mTOR and JNK/MAPK signaling cascades, further supports its role in promoting tumor growth and survival." (PMID 41303526, 2025). "Although, mTOR inhibitors have been used in combined treatment schedules for many tumor types, no comparable long-term treatment results have been achieved." (PMID 40183103, 2025). "Tumor profiles differed, with the absence of somatic drivers in the PI3K/mTOR pathway in patients with germline P/LP variants versus those without (P = .023)." (PMID 40072012, 2025). "To further investigate the impact of prepared TMTP1-TSRP-EVs on the primary immune checkpoint resistance in PI3K-mutant NSCLC, we co-cultured EVs from different groups with A549 cells and assessed their effects on the PI3K/AKT/mTOR pathway, PD-L1 protein, CD8+ T cells, and tumor cells." (PMID 40328748, 2025). "The main outcomes were differences in circulating tumor DNA profiles and use of phosphoinositide 3-kinase (PI3K), mammalian target of rapamycin (mTOR), and cyclin-dependent kinase 4/6 (CDK4/6) inhibitors between Black and White patients with metastatic breast cancer." (PMID 40009379, 2025). "Furthermore, it highlighted the enrichment of key tumor-regulating pathways, including IFN-γ, PI3K-Akt-mTOR, EMT, inflammation, and innate immune responses." (PMID 40669378, 2025). "FAM72B may also participate in the activation of signaling pathways that facilitate tumor progression, such as the PI3K/AKT/mTOR pathway." (PMID 41153357, 2025). "The combination of the GLI1/2 inhibitor GANT61 and the PI3K/mTOR inhibitor PI103 synergistically induces apoptosis in RMS cell lines and primary cells (CI < 0.2) and suppresses clonogenicity, three-dimensional growth, and in vivo tumor progression." (PMID 40508013, 2025).
tumor (continued). "Tumor maximal thickness, widely used as the main measurement to evaluate the size of RAH lesions, was reported to be significantly reduced in the treatment of mammalian targets with rapamycin (mTOR) inhibitors for TSC." (PMID 40486194, 2025). "However, various aberrant signaling pathways are involved in the maintenance and propagation of this tumor subpopulation, including TGF-β, Wnt/β-catenin, Notch, Hedgehog, PI3K/Akt/mTOR, NF-κB signaling, as well as the Hippo-YAP/TAZ pathways." (PMID 39940882, 2025). "Understanding Smurf1's regulation in the mTOR‐TFEB axis, which balances tumor growth and stress‐induced cell homeostasis, may provide novel therapeutic targets for tumor progression and drug resistance." (PMID 40958774, 2025). "BCL-2 activity is directly controlled by AKT/mammalian target of rapamycin (mTOR) signalling, and a combination of crizotinib with mTOR inhibitor Torin2 prolonged survival of mice with ALKF1174L/MYCN NB tumours, which overexpress BCL-2 and are resistant to crizotinib." (PMID 41511287, 2025). "Additionally, LMP2A has been shown to activate PI3K/Akt, leading to mTOR-mediated downstream inhibition of 4E-BP1 and upregulation of c-Myc, and plays a role in the formation of EBV-induced vasculogenic mimicry (tumor that mimics blood vessels)." (PMID 40872852, 2025). "We next explored the role of mTOR and EGFR pathway activation in EY-mediated tumor initiation." (PMID 39779672, 2025). "Furthermore, it can improve the body’s immune surveillance against tumors by regulating tumor-related signaling pathways such as JAK-STAT, PI3K/Akt/mTOR, thereby slowing down tumor progression." (PMID 40704062, 2025). "Additionally, both in vitro and in vivo experiments were undertaken to validate the tumor-suppressing capabilities of SERPING1 specifically and regulation of TSC2/mTOR pathway in LUAD." (PMID 39962118, 2025). "Moreover, BEZ-235 has been shown to inhibit PI3K/mTOR-dependent signaling nodes such as AKT, S6, and 4EBP1, reducing MMP-2 expression and invasive migration across multiple tumor types." (PMID 40869090, 2025). "On the contrary, protein kinase inhibitors, protein synthesis inhibitors, and mTOR inhibitors can induce the expression of HOX genes, so we can induce the expression of HOX genes as tumor suppressors by using related small molecular drugs, thus inhibiting the proliferation of tumor cells." (PMID 39980564, 2025). "In liver cancer, overexpression of the HGF/c‐Met pathway leads to excessive HGF secretion by mesenchymal cells, synergising with pathways such as PI3K/Akt/mTOR, MAPK/ERK, and Rho GTPases to promote tumour proliferation, remodel the cytoskeleton, and facilitate metastasis." (PMID 40525649, 2025). "Although some studies have shown that Osthole, an active ingredient in MQSD, can attenuate the phosphorylation levels of AMPK, Akt and mTOR in HCT116 and SW480 cells, inducing cellular ferroptosis and exerting anti‐tumour effects, these findings are specific to tumour cells." (PMID 40586853, 2025). "Remarkably, metformin inhibited the mTOR activity and helped downregulating the expression of ERCC1, thus inhibiting DNA repair and overcoming the resistance of cisplatin-based chemotherapy in the LLC tumor-bearing mice." (PMID 39776799, 2025). "Similarly, the dual blockade of mTOR and PI3K is under investigation as a way to prevent the feedback activation of tumor survival pathways." (PMID 40429384, 2025). "Thus, the knockdown of SLC25A20 severely reduces the activity of mTOR due to a decrease in FAO-dependent ATP, and these changes are a major contributor to invasive tumor changes and reduced progression to PDAC." (PMID 40521210, 2025).
tumor (continued). "Although the tumor-suppressive properties of miRNA-195-5p have been acknowledged, the precise pathways through which it exerts its effects, particularly concerning MYB and the PI3K/AKT/mTOR signaling cascade, remain inadequately investigated." (PMID 41141380, 2025). "In NSCLC cells the ErbB family plays these pivotal roles by ligand activation, due to the release of cognate ligands, often due to their transactivation by GPCRs, resulting in stimulation of a number of potent tumor growth cascades (i.e., MAPK, PI3K/AKT, STAT, mTor, RAS, and RAF cascades)." (PMID 41007372, 2025). "Similarly, mTOR inhibitors like Rapamycin suppress SASP expression by modulating mTOR-ZFP36L1 signaling, reducing tumor growth and resistance in HNC models." (PMID 41463272, 2025). "PTK6 has been demonstrated to enhance various aspects of tumor progression, such as cell proliferation, migration, invasion, and survival, through the modulation of several signaling pathways, including Ras/MAPK, PI3K/Akt/mTOR, and JAK-Stat." (PMID 40809015, 2025). "Furthermore, naringenin inhibits the PI3K/Akt/mTOR and IL-6/STAT3 signaling pathways, key oncogenic routes frequently exploited by BPA to drive tumor progression." (PMID 41440754, 2025). "Across diverse tumor models, IVM demonstrates consistent antitumor activity through the induction of apoptosis, oxidative stress, mitochondrial dysfunction, and inhibition of key signaling pathways, including NF-κB, mTOR/STAT3, and importin β." (PMID 41155573, 2025). "These combined alterations may have created a self-reinforcing loop in which tumor-derived cytokines activated the JAK/STAT pathway, while concurrent activation of PI3K/AKT/mTOR signaling promoted megakaryocytic proliferation and platelet production." (PMID 41438978, 2025). "At this stage, macroautophagy declines, evidenced by the accumulation of p62, activating NRF2 and promoting mTOR signaling driving tumor cell proliferation and growth, independent of growth factors." (PMID 40789840, 2025). "Current studies have demonstrated that TUSC2 might play a tumor-suppressing role through inducing apoptosis, arresting the G1 cell cycle, and inhibiting proliferation-related kinases, e.g., EGFR, mTOR, and AKT." (PMID 40243558, 2025). "This study introduced the BCIS score, distinguishing invasion from non-invasion cells, linked to PI3K/AKT/mTOR pathways, offering insights into BRCA prognosis and tumor aggressiveness." (PMID 40204712, 2025). "Additionally, the tumor stem cell population exhibits activation of the RAS/RAF/MEK/ERK, PI3K, AKT, and mTOR survival signaling pathways that provide growth advantage to the cancer-initiating stem cell population." (PMID 40141171, 2025). "To investigate whether mTOR inhibition enhances the therapeutic efficacy of [177Lu]Lu-DOTA-CCK2R-dimer, we evaluated their combination in an AR42J tumor-bearing mouse model." (PMID 40963930, 2025). "Ultimately, the combination reduced tumor weight and volume and decreased the expression of the Ki-67 proliferation marker, demonstrating synergistic prevention against gastric cancer via the PI3K/Akt/mTOR pathway." (PMID 40572668, 2025). "Additionally, administration of the autophagy inhibitor 3-methyladenine (3-MA) led to increased MTOR expression and downregulation of ATG5, ATG7, and BECN1, resulting in reduced tumor volume and elevated apoptosis cell death." (PMID 41502518, 2025).